CGAS (cyclic GMP-AMP synthase)
Diseases named in the same sentence as CGAS in open-access papers (continued):
Sharing a sentence is not in itself a finding about the gene and the disease.
autoimmune disease (continued). "This proof-of-concept study reveals the cGAS-dependent immunogenicity of nucleosomes and highlights the potential roles of circulating nucleosomes in autoimmune diseases, inflammation, and antitumour immunity." (PMID 32958884, 2020). "It has been demonstrated that some severe autoimmune diseases are related to mis-activation of cGAS." (PMID 32474700, 2020). "Elucidation of PTMs will help develop novel therapeutics targeting cGAS, boosting host immunity to inhibit pathogen infection or downregulate innate immune response to ameliorate autoimmune disease." (PMID 33105828, 2020). "Our study provides an explanation for the development of autoimmune diseases in these patients and suggests that the cGAS–STING signaling axis can be a promising therapeutic target." (PMID 33273464, 2020). "In AGS autoimmune disease, where neuronal RNase H2 function is compromised, genome instability can lead to the formation of micronuclei and activation of cGAS/STING, which then triggers an inflammatory response." (PMID 31833079, 2020). "The anti-viral pattern recognition receptor STING and its partnering cytosolic DNA sensor cGAS have been increasingly recognized to respond to self DNA in multiple pathologic settings including cancer and autoimmune disease." (PMID 33552072, 2020). "As a classic pathway, components of cGAS pathway, up and down stream regulatory factors and roles in autoimmune diseases and tumor immunity have been fully described and summarized." (PMID 35006429, 2020). "Upon sensing cytosolic DNA, the enzyme cGAS induces innate immune responses that underpin anti-microbial defenses and certain autoimmune diseases." (PMID 33273464, 2020). "This study revealed the cGAS-dependent immunity of extracellular nucleosomes and highlights the potential roles of circulating nucleosomes in autoimmune diseases, inflammation, and antitumour immunity." (PMID 32958884, 2020). "Taken together, these results support dysregulation of the cGAS/STING signaling axis in several autoimmune diseases." (PMID 28934246, 2017). "Given the widespread expression of cGAS, RLRs, and GBPs across numerous tissues, systemic administration of their agonists could potentially lead to autoimmune diseases or cytokine storms." (PMID 40362284, 2025). "We explored whether targeting cGAS methylation could be a viable strategy for treating self-DNA-induced autoimmune diseases." (PMID 40595456, 2025). "Mutation of TREX1 in autoimmune diseases, dissociating TREX1 from the endoplasmic reticulum, disrupts the localization of TREX1 in micronuclei, reduces micronucleus-damaged DNA degradation, and enhances cGAS activation." (PMID 39759116, 2025). "Given that cGAS hyperactivation can trigger autoimmune diseases such as AGS, we found that KDM4B deficiency or its inhibitor JIB-04 significantly suppresses cGAS activation and IFN expression, providing a novel therapeutic target and strategy for autoimmune diseases." (PMID 40595456, 2025). "Thus, membrane binding of the cGAS is a strategy to avoid its overactivation against cytosolic dsDNA to prevent the increased incidence of autoinflammatory or autoimmune diseases." (PMID 38339107, 2024). "Consequently, the cGAS-STING signaling pathway is expected to be a new target for the treatment of autoimmune diseases." (PMID 38831059, 2024). "Whereas elevated levels of cGAS have been associated with a variety of autoimmune diseases, such as SLE, AGS, and IBD, lack of cGAS has been linked with several types of cancer." (PMID 39050748, 2024). "Thus, our findings place DM2 among other autoimmune diseases resulting from cGAS/STING-induced chronic ISG upregulation and autoimmunity and into the larger context of type I interferon-driven disease." (PMID 38378748, 2024). "However, abnormal activation of the cGAS-STING pathway by self-DNA can also lead to autoimmune diseases and inflammatory disorders." (PMID 39445027, 2024). "cGAS Antagonists used in inflammatory or autoimmune diseases." (PMID 39183465, 2024).
autoimmune disease (continued). "The discovery of cyclic GMP-AMP synthase (cGAS), the most interested PRRs in recent years, is a significant milestone in the field of DNA sensing, which plays a crucial role in infectious diseases, autoimmune diseases, cancers and other diseases." (PMID 38515746, 2024). "However, excessive release of interferon and inflammatory factors due to over-activation of the cGAS-STING pathway is an important cause of the development of related inflammatory and autoimmune diseases." (PMID 39148120, 2024). "Therefore, the inhibition of cGAS-STING is a promising therapeutic target for autoimmune diseases, but is limited to the diseases that are cGAS-dependent." (PMID 39872301, 2023). "Thus, targeting the activation of cGAS-STING signaling is a potential treatment for self-DNA-induced autoimmune diseases." (PMID 37120570, 2023). "Considering that the engagement of innate immune precedes and ignites the adaptive immune response, and activated T helper cells are the major mediators in autoimmune diseases, the application range of iZAK2 may be wider than cGAS-STING inhibitors." (PMID 39872301, 2023). "Because cGAS is critical to multiple autoimmune diseases, FAs might also be involved in autoimmunity by dissolving cGAS–DNA PS." (PMID 36950761, 2023). "The cGAS-STING signaling is activated by pathogenic DNA from DNA virus or intracellular bacteria, and endogenous DNA, including mitochondrial and nuclear DNA in the cytosol in response to mitochondria stress, radiation therapy or autoimmune disorders." (PMID 37020586, 2023). "For example, inhibitors that negatively modulate the cGAS–STING pathway may be used to reduce the development of autoimmune disorders and local inflammation." (PMID 37686127, 2023). "The cGAS-STING pathway is a crucial mechanism in the cellular sensing of DNA and the activation of innate immunity, and it is implicated in various infectious and autoimmune diseases, such as psoriasis and SLE." (PMID 37049889, 2023). "Notably, these autoimmune phenotypes are fully eliminated by depletion of cGAS, suggesting an indispensable role of cGAS in autoimmune diseases triggered by self-DNA18." (PMID 36217001, 2022). "Frequently, these autoimmune diseases are the result of mutations that inactivate a negative-regulator of cGAS-STING signaling named three-prime repair exonuclease 1 (TREX1)." (PMID 35879334, 2022). "Notably, the discovery of this binding domain provides a powerful platform for the structural insights into nucleosome inhibition of cGAS activity, thus providing opportunities for the treatment of autoimmune diseases." (PMID 35536585, 2022). "Further in vivo studies will be necessary to assess whether NR modulates cGAS/STING-mediated type I IFN signaling, which is implicated in autoimmune diseases, including SLE." (PMID 35025762, 2022). "cGAS is suggested to regulate infectious diseases, autoimmune diseases, and cancer." (PMID 35108342, 2022). "Importantly, the knock-outing of the STING gene would ameliorate the pathological features of the STING-relevant autoimmune disease, which indicate that the cGAS-STING-TBK1 axis is a promising therapeutic target for various autoimmune diseases." (PMID 36172373, 2022). "Therefore, targeting the cGAS-STING-TBK1 axis has become a promising strategy in therapy of autoimmune diseases." (PMID 36172373, 2022). "This localization avoids the activation of cGAS by its own trace DNA, which may lead to autoimmune diseases." (PMID 35536585, 2022). "The STING/cGAS signaling pathway is involved in the pathogenesis of autoimmune diseases." (PMID 36591278, 2022). "However, aberrant activation of the cGAS-STING pathway by self-DNA can also lead to autoimmune diseases, such as AGS." (PMID 35619184, 2022). "In combination with existing virtual screening approaches, our study could provide theoretical guidance in the search for new cGAS inhibitors and thus be helpful in the treatment of autoimmune diseases." (PMID 33503880, 2021).
autoimmune disease (continued). "Collectively, these data reveal that inhibition of cGAS activity by PAH could potentially provide a therapeutic strategy for cGAS-mediated autoimmune diseases." (PMID 33968056, 2021). "As Trex1−/− mice are mechanistically characterized by aberrant activation of cGAS, we sought to determine whether miR-23a/b could be utilized to treat cGAS-mediated autoimmune diseases." (PMID 33767433, 2021). "On the other hand, abnormal activation of cGAS or STING is closely related to autoimmune diseases." (PMID 34867409, 2021). "In the context of potential STING activity in human autoreactive B cells and human autoimmune diseases, however, the threshold for cGAS/STING pathway activation and type I interferon secretion could be different." (PMID 34938294, 2021). "The cGAS-STING pathway plays an important role in innate immunity, but cGAS can also be activated by the body’s abnormal DNA to cause tissue damage or autoimmune diseases, such as Aicardi-Goutières syndrome (AGS), systemic lupus erythematosus (SLE), primary biliary liver disease." (PMID 34867409, 2021). "Although cGAS plays critical pathophysiological roles in autoimmune diseases, aging, and cancer, the cGAS gene has not been reported to be amplified/mutated/deleted in these human diseases." (PMID 33927185, 2021). "cGAS also plays a key role in the regulation of autoimmune diseases and tumor immunity." (PMID 34899698, 2021). "Moreover, cGAS-dependent two-step synthetic 2’,5’-cGAMP can be used to develop specific inhibitors to treat autoimmune diseases related to cGAS/STING signaling." (PMID 35046953, 2021). "Taken together, these data indicate that inhibition of cGAS expression by miR-23a/b could be a potential therapeutic strategy for autoimmune diseases." (PMID 33767433, 2021). "Therefore, how much patients with autoimmune disease or cancer will benefit from cGAS-STING immunotherapy requires further investigation." (PMID 34867409, 2021). "Hence, cGAS is a vital drug target for treating autoimmune diseases and for preventing autoinflammation in therapeutic strategies against cancers." (PMID 33503880, 2021). "This opens many interesting possibilities for cGAS involvement in autoimmune diseases that can be incorporated into the “X chromosome-nucleolus nexus” hypothesis." (PMID 34968240, 2020). "Thus the tight nuclear tethering of the cGAS maintains its resting stage and prevents autoinflammatory and autoimmune diseases." (PMID 33643304, 2020). "In summary, cGAS is an essential protein for the innate immune response to cytosolic DNAs and has been considered as a potential valuable target for the therapeutic development to improve the treatment of human autoimmune disorders." (PMID 32180716, 2020). "Importantly, cGAS also detects mitochondrial DNA and nuclear DNA mis-located in the cytosol under certain conditions, which plays a key role in certain autoimmune diseases and inflammatory responses during radiotherapy for cancer." (PMID 32474700, 2020). "Inhibition of cGAS may be an effective strategy for treating autoimmune diseases such as Aicardi-Goutieres syndrome and systemic lupus erythematosus." (PMID 32180716, 2020). "Due to the significant role of cGAS in innate immunity, small-molecule inhibitors of cGAS may be used not only for further exploring cGAS-mediated DNA sensing mechanisms and innate immunity regulation, but also for treatments of autoimmune disorders." (PMID 32180716, 2020). "Therefore, identifying mechanisms to prevent inappropriate activation of cGAS is crucial for the treatment of the relevant autoimmune diseases." (PMID 33273464, 2020). "The cGAS-MITA pathway also detects leaked or aberrant accumulated self DNA in the cytoplasm under certain pathological conditions, such as virus induced cell death, DNA damage, mitochondria damage, gene mutations, which results in autoimmune diseases." (PMID 29546673, 2018).
autoimmune disease (continued). "cGAS also plays important roles in some autoinflammatory and autoimmune diseases and may be involved in immune responses targeting cancer cells." (PMID 28808967, 2017). "The evidence linking activation of the cGAS pathway to autoimmune disease suggests that cGAS inhibitors may have therapeutic efficacy." (PMID 28934246, 2017). "Given that cGAS senses DNAs in a sequence-independent manner, any aberrant activation of the cGAS by cytosolic DNAs contributes to the pathogenesis of chronic inflammation and autoimmune diseases." (PMID 28095500, 2017). "The potential role of cGAS in inflammatory and autoimmune disorders has recently been uncovered." (PMID 26819496, 2015). "Autoimmune diseases in Trex-1 and DNase II-deficient mice were shown to be dependent on the cGAS-STING pathway, and other murine studies have demonstrated the contribution of the cGAS-STING pathway to enhancing type I IFN responses in lupus or lupus-like mouse models." (PMID 40746538, 2025). "Dysregulation of cGAS function is therefore conceivable as a trigger for aberrant innate immune activation, potentially contributing to the pathogenesis of a spectrum of diseases, including autoimmune disorders, neurodegenerative conditions, and organ fibrosis." (PMID 40470467, 2025). "Abnormal cGAS-STING pathway activation may lead to the occurrence of autoimmune diseases." (PMID 38831059, 2024). "However, the cGAS-STING signaling pathway is not limited to autoimmune diseases and inflammation, but plays an important role in many physiological and pathological processes, such as host defense against microbial infections, antitumor immunity, cellular senescence, and autophagy." (PMID 38066431, 2023). "At present, studies have confirmed that cGAS-STING and its downstream pathways cause IFN-I-type inflammatory responses in monocytes and dendritic cells of pSS patients and are also involved in the development of various autoimmune diseases, such as SLE, RA, and AGS." (PMID 37786436, 2023). "Thus, this group introduced a promising role of aspirin, which could directly acetylate cGAS to inhibit cGAS activation, as a therapeutic strategy in treating autoimmune diseases, such as Aicardi–Goutieres syndrome (AGS)." (PMID 36139387, 2022). "Autoimmune disease-associated TREX1 mutations in surface-exposed residues (e.g., E198K, K66R, P132A, A223T) may also alter binding to protein partners, post-translational modifications, and interaction with cGAS-DNA condensates." (PMID 35879334, 2022). "In addition, miR-23a/b treatment was effective in alleviating cGAS-mediated autoinflammatory responses in the Trex1−/− mouse model, indicating that miR-23a/b could be used to treat self DNA-induced autoimmune diseases." (PMID 33767433, 2021). "Thus, preventing cGAS-STING activation could provide therapeutic benefit to treat TREX1-mediated autoimmune disease." (PMID 33868310, 2021). "Moreover, cGAS is significantly upregulated in the Trex1−/− mouse autoimmune disease model." (PMID 33767433, 2021). "However, with progress in this area of research, studies focused on autoimmune diseases and chronic inflammatory conditions that may be relevant to cGAS–STING pathways have been conducted." (PMID 34906241, 2021). "Thus, our research identifies a feasible approach to treat cGAS-mediated autoimmune diseases." (PMID 33767433, 2021). "Thus, inhibition of cGAS activity is a promising therapeutic strategy for autoimmune diseases." (PMID 33503880, 2021). "Hence, the activity of cGAS-STING signaling in both cytosol and nucleus is a highly controlled process, and any impairment may predispose the host to severe autoinflammatory or autoimmune diseases that may also develop different cancers." (PMID 33643304, 2020). "Therefore, manipulation of the cGAS signaling pathway could be beneficial for cGAS-mediated autoimmune diseases." (PMID 32863951, 2020). "Hence, MYSM1-based therapeutics may prove beneficial in cGAS-STING-based autoimmune diseases (SLE and IBD)." (PMID 33643304, 2020).
autoimmune disease (continued). "Finally, the roles of cGAS in autoimmune diseases and antitumor immunity have drawn more and more attention, but the regulation mechanisms of cGAS in these processes are still largely unknown." (PMID 29546673, 2018). "Interestingly, we observed that SENP7 was significantly up-regulated in patients with autoimmune disease, indicating that SENP7 might synergize the action of cGAS in the pathogenesis of certain autoimmune disorders." (PMID 28095500, 2017). "In autoimmune diseases like SLE, the overactivation of the cGAS-STING pathway can lead to excessive immune responses, with RNF185 being a key E3 ubiquitin ligase implicated in SLE pathogenesis." (PMID 40028324, 2025). "Taken together, lysosomal DNA stress can promote autoinflammatory and autoimmune diseases via TLR9, cGAS-STING and AIM2 activation." (PMID 40037613, 2025). "When nuclease activity is uncontrolled, large amounts of dsDNA are cleaved, which are recognized by DNA receptors and activate the cGAS-STING pathway, thereby triggering autoimmune diseases." (PMID 39759116, 2025). "Importantly, we show that targeting cGAS demethylation, either through K350R mutation or KDM4B inhibition with JIB-04, ameliorates autoimmune manifestations in both Trex1−/− mice and AGS patient PBMCs, presenting a promising therapeutic strategy for self-DNA-induced autoimmune disorders." (PMID 40595456, 2025). "Conversely, the development of inhibitors targeting cGAS or STING functions represents another therapeutic approach, particularly for treating complex inflammatory and autoimmune diseases." (PMID 41438738, 2025). "Nonetheless, over-reactivity to self-nucleic acids leads to the sustained production of type I interferon (IFN), mediated either by cGAS or RLR, contributing to the pathogenesis of certain autoimmune diseases, such as Aicardi–Goutières syndrome (AGS)." (PMID 40149865, 2025). "Mutations in TREX1 have been identified in patients with Aicardi-Goutières syndrome (AGS), where accumulated cytoplasmic self-DNAs chronically activate cGAS-mediated type I IFN production, driving systemic inflammation and autoimmune disorders." (PMID 40595456, 2025). "The cGAS–STING pathway has been identified as a therapeutic target of autoinflammatory and autoimmune diseases." (PMID 39873292, 2025). "The cGAS-STING signaling pathway is pivotal in the onset and progression of various autoimmune diseases and chronic inflammation." (PMID 39540037, 2024). "A thorough summary of the many functions of the cyclic GMP-AMP synthase (cGAS)-stimulator of interferon genes (STING) pathway in malignancies and autoimmune disorders has recently been published." (PMID 39114669, 2024). "In summary, the loss of the DNA clearance function in vivo leads to chronic activation of the cGAS–STING signaling pathway, and this then leads to autoimmune diseases." (PMID 38525112, 2024). "The cGAS-STING pathway plays an important role in the pathogenesis and progression of cancers and autoimmune diseases." (PMID 38999073, 2024). "The cGAS-STING pathway affects autophagy, senescence, and antitumor immunity, and overactivation of this pathway results in inflammatory and autoimmune disorders." (PMID 39183465, 2024). "Ventus Therapeutics has advanced VENT-03, the first cGAS-STING pathway inhibitor, into phase I clinical trials, thus initiating a new journey in the treatment of autoimmune diseases using cGAS-STING inhibitors." (PMID 39183465, 2024). "Inhibition of FABP5 triggers activation of the cGAS‐STING pathway, inducing IL‐10 production and promoting the inhibitory activity of Treg, thus attenuating autoimmune disorders." (PMID 38500390, 2024). "In summary, the results reported here introduce a research area in targeting the cGAS/STING pathway and opens horizons for the regulation of STING in the context of autoimmune disorders." (PMID 38811577, 2024).